DEK (DEK proto-oncogene)
Diseases named in the same sentence as DEK in open-access papers (continued):
Sharing a sentence is not in itself a finding about the gene and the disease.
cancer (continued). "To date, DEK::AFF2 carcinoma has been considered a malignancy confined to the upper respiratory tract, with only one primary lung SCC with DEK::AFF2 fusion reported in a 26-year-old female never-smoker." (PMID 40299135, 2025). "Here, we report the first documented case of primary laryngeal SCC with DEK::AFF2 fusion, suggesting that this carcinoma may not be restricted to the sinonasal tract and skull base but could potentially arise throughout the respiratory tract epithelium." (PMID 40299135, 2025).
tumor (58 papers, 2005 to 2026). "The tumor cone precursors were also characterized by the expression of DEK and BCOR, despite suggested loss of copy of number." (PMID 34003213, 2021). "RON (Receptor d’ Origin nantaise), a Tyrosine kinase receptor has been implicated in tumour progression and is a target of DEK." (PMID 32257110, 2020). "In conclusion, we have found a surprising down-regulation of DEK expression specifically in CD138positive plasma cells, even in the setting of copy number gains of the DEK gene associated with neoplasia." (PMID 28558048, 2017). "In high-grade neuroendocrine carcinoma of lung, overexpression of DEK is associated with tumor initiation activity and poor prognosis." (PMID 27057626, 2016). "The loss of DEK inhibited cell proliferation and migration in vitro, delayed tumor growth in xenograft mouse model and suppressed mouse splenic vein metastasis." (PMID 27057626, 2016). "Interestingly, almost all tumour-associated proteins, including the oncogenes DEK and CHD4 and the tumour-suppressor gene MYH9, were expressed at lower levels in LM4 than in T4." (PMID 36691026, 2023). "DEK deficiency in different tumor cells has been shown to increase their sensitivity to DOX." (PMID 35769815, 2022). "Here, for the first time, we utilize cell culture, mouse, and human dataset models to demonstrate that DEK expression in mammary tumors does, indeed, create a potentially pro-tumorigenic microenvironment through the M2 polarization of tumor associated macrophages." (PMID 32708944, 2020). "Together, our data demonstrate that by regulating the production of multiple secreted factors, DEK expression in BC cells creates a potentially immune suppressed tumor microenvironment, particularly by inducing M2 tumor associated macrophage (TAM) polarization." (PMID 32708944, 2020). "We found that DEK overexpression was sufficient to increase gross esophageal squamous cell carcinoma incidence and caused a trend toward increased cellular proliferation in adjacent non-tumor tissue." (PMID 29538372, 2018). "Together these three studies implicate DEK as a tumor-associated antigen that may mediate interactions between lymphocytes and tumor cells." (PMID 26425120, 2015). "Combined, our data strongly indicate that the expression of DEK within solid tumors, particularly breast cancer, results in the differential expression of several cytokines and chemokines that create a pro-tumorigenic milieu to drive M2 polarization of tumor associated macrophages." (PMID 32708944, 2020). "The SPOP Y87N mutant disrupts DEK degradation, promoting DEK accumulation and enhancing sphere-forming capacity in prostate epithelial cells, suggesting a role in tumor initiation." (PMID 40521202, 2025). "Another histone chaperone, DEK, a tumor-promoting factor, has been reported to potentially create an immune-suppressed tumor microenvironment." (PMID 36768989, 2023). "DEK silencing in U251 cells induced apoptosis and cell cycle arrest, suggesting DEK’s role in promoting tumor formation and progression." (PMID 37762371, 2023). "In the current study, we revealed that the histone chaperones HSPA8 and DEK strongly influence the tumor immunity of HCC." (PMID 36768989, 2023). "Although the current study reveals the effect of the histone chaperones HSPA8 and DEK on tumor immunity in HCC, it has certain limitations and drawbacks." (PMID 36768989, 2023). "In conclusion, the histone chaperones HSPA8 and DEK are closely related to the tumor immunity of HCC." (PMID 36768989, 2023). "In promoting tumorigenesis and tumor progression, DEK has been shown to promote cell growth and self-renewal, while inhibiting cell differentiation, premature and apoptosis of malignant cells." (PMID 35563178, 2022). "DEK silencing induces apoptosis of tumor cells by activation of caspase-9 and subsequent cleavage and activation of procaspase-3, which then cleaves different cellular endogenous substrates leading to cell death." (PMID 35769815, 2022).
tumor (continued). "Crowberry inactivated the PI3K/Akt signaling pathway by regulating DEK in vitro and significantly inhibited tumor growth by downregulating the DEK expression in xenograft models." (PMID 35698073, 2022). "Further, the IHC staining was performed, indicating that Ki67 and DEK were significantly decreased in the xenograft tumor tissues compared with the control group." (PMID 35698073, 2022). "The DEK KD mice were less aggressive and showed smaller tumor sizes than the mice we injected with SCR Jurkat cells." (PMID 35769815, 2022). "To investigate the effect of DEK silencing in vivo, we established a tumor model by subcutaneously injecting DEK-silenced Jurkat cells or control cells into female adult BALB/C nude mice." (PMID 35769815, 2022). "The chromatin associated oncogene, DEK, is a RON-stimulated protein that promotes tumor cell proliferation." (PMID 36067206, 2022). "Recently, it has been shown that DEK induces M2 macrophage polarization and creates an immune-suppressed tumor microenvironment." (PMID 34065619, 2021). "The results showed that DEK overexpression increased the overall incidence of esophageal SCC as well as cellular proliferation in adjacent non-tumor tissues." (PMID 32656741, 2020). "In conclusion, DEK protein is overexpressed in human SCCs in multiple organs, and it plays an active role in tumor initiation and maintenance." (PMID 32656741, 2020). "They assessed the intensity of DEK protein expression and the proportion of DEK-positive tumor cells relative to the adjacent normal tissue." (PMID 32656741, 2020). "The work presented here is the first description of how DEK expression in tumor cells can promote tumor progression via cell extrinsic mechanisms." (PMID 32708944, 2020). "In this study, we selected DEK for the biological function study in GC, due to its upregulation in both tumor and blood stream." (PMID 31766266, 2019). "As an oncogene, DEK involves in regulation of various cellular metabolisms and plays an important role in tumor growth and progression." (PMID 29228721, 2017). "Compared to normal tissue, DEK expression is upregulated in most surveyed tumor types, including breast, hepatocellular carcinoma, colorectal cancer, and, recently, OPSCC." (PMID 28423581, 2017). "In epithelial cells, decreased DEK expression induces senescence and reduces tumor formation, whereas it increases the number of myeloid progenitor cells in mice and stimulates myeloid colony formation in vitro." (PMID 28558048, 2017). "In this study, we demonstrated that DEK knockdown attenuated cell proliferation, migration, invasion, and angiogenesis in vitro, and delayed tumor growth and mouse caudal vein metastasis in xenograft mouse model." (PMID 29228721, 2017). "Since VEGF is a key regulator of tumor angiogenesis under normoxic and hypoxic conditions, we screened a transcription factor array, and identified DEK as a regulator of VEGF expression for the first time." (PMID 26988756, 2016). "DEK promotes tumor angiogenesis and growth in nude mice in HIF-1α-dependent and -independent manners." (PMID 26988756, 2016). "Third, and finally, DEK secretion by macrophages also has two major implications on potential tumor microenvironments." (PMID 26425120, 2015). "Our data identified IRAK1 as a component of the DEK-dependent transcriptome whose expression in HNSCC contributes to tumor cell survival." (PMID 26527316, 2015). "The dysregulation of DEK can disturb normal cell functions and potentiate pathogenesis resulting in transformation, chemoresistance, inflammation, and tumor development." (PMID 26425120, 2015). "This relation between DEK expression and irinotecan therapy was confirmed in three tumor samples cultured ex-vivo with SN38 for 24 hours." (PMID 25515240, 2014). "Here we define specific oncogenic activities of DEK in CRCs in vitro, and identify a molecular mechanism through which DEK contributes to tumor growth." (PMID 25340858, 2014).
tumor (continued). "Western blot data showed robust DEK protein expression in CRC tissues compared with the matched adjacent non-tumor tissues." (PMID 25340858, 2014). "Subsequent studies have repeatedly identified DEK as a frequently overexpressed gene in a number of neoplasms." (PMID 25340858, 2014). "To demonstrate the role of DEK on CRC, we measured DEK protein levels in four cases of CRC with matched adjacent non-tumor fresh tissues." (PMID 25340858, 2014). "This notion would be compatible with the previous observation that DEK is essential for tumor cells but dispensable for their normal counterparts." (PMID 25216995, 2014). "Our findings are perhaps the first to report on the prognostic significance of DEK in HCC, and proved DEK as a potential biomarker for HCC to evaluate its role in tumor progression and prognosis." (PMID 24353627, 2013). "Based on our data obtained from a relatively small sample size of 38 tumor samples, DEK protein is present in most low grade tumor tissue as compared to high grade." (PMID 21663673, 2011). "Upon comparison of DEK protein levels in tissue and in the voided urine from TCC patients, we found 12 out of 18 samples were consistent for DEK expression in tumor tissue and voided urine." (PMID 21663673, 2011). "DEK protein is present in 100% of low malignant potential (LMP) TCC tissue and 93% in low grade TCC whereas only 71% of high grade tumor tissues were positive for DEK expression." (PMID 21663673, 2011). "In accord with previous reports, expression of E2F3 mRNA and DEK mRNA were often increased in tumor compared to normal tissues." (PMID 15876350, 2005). "Expression of E2F3 as well as DEK increased on average in tumor vs. normal tissues (3-fold and 2.5-fold, resp)." (PMID 15876350, 2005). "Because DEK is a secreted HS-binding protein, we hypothesized that PG545 might sequester DEK in the tumor microenvironment, thereby reducing its HSPG-mediated cellular uptake and nuclear localization." (PMID 37550562, 2023). "In conclusion, HSPA8 and DEK greatly affect the tumor immunity of HCC and could potentially be regarded as biomarkers for precisely predicting the effect of immunotherapy in HCC." (PMID 36768989, 2023). "Although the DEK gene is related to tumor processes in humans, it is involved in stages of cell differentiation, and complementarity to the KMT2E gene, which acts on cell proliferation, allows us to reinforce the possibility that ALA-L animals are less precocious." (PMID 35629975, 2022). "DEK participates in tumor cell proliferation, apoptosis invasion and differentiation by regulating several signaling pathways, such as Akt signaling pathways, thereby promoting tumor cell growth and infiltration." (PMID 35698073, 2022). "DEK plays important roles in the proliferation, migration, and metastasis of tumor cells." (PMID 35698073, 2022). "It is important to note that DEK overexpression on its own in vivo is not tumorigenic but requires initiating mutations through chemical carcinogenesis or cooperating tumor initiating mutations." (PMID 36275000, 2022). "IHC staining of tumor tissue showed that Ki67 and DEK were reduced." (PMID 35698073, 2022). "The DEK proto-oncogene (DEK) has been involved in neoplasms but remains unexplored in T-ALL." (PMID 35769815, 2022). "DEK may act as a structural regulatory protein that regulates the expression and function of various human genes in tumor cells." (PMID 35563178, 2022). "DEK-induced cytokine dysregulation is associated with M2 macrophage (TAM) polarization, creating a potentially pro-tumor microenvironment through M2 polarization of tumor-associated macrophages." (PMID 35742899, 2022).
tumor (continued). "Specifically, we showed that DEK expression in human breast cancers correlates with several differentially expressed genes identified by RNA-Sequencing in our murine model, and that DEK expression positively correlated with “wound-healing” and “macrophage regulation” tumor phenotypes." (PMID 32708944, 2020). "We hypothesized that one mechanism of DEK-mediated tumor progression would be the creation of a pro-tumorigenic microenvironment that would impact the anti-tumor immune response." (PMID 32708944, 2020). "Therefore, this work sought to explore the transcriptional impact of DEK over-expression in breast cancers and the downstream consequences to the tumor microenvironment." (PMID 32708944, 2020). "DEK is highly expressed in inflammatory diseases and tumours." (PMID 33124760, 2020). "Interestingly, no mutations have been reported in the coding sequence of human DEK gene in tumor tissues." (PMID 32656741, 2020). "Indeed, we confirmed a strong positive correlation between DEK and a previously identified tumor phenotype, proliferation." (PMID 32708944, 2020). "Furthermore, we revealed the inhibitory effect of DEK depletion on tumor growth and progression in a xenograft tumor model in mice." (PMID 29228721, 2017). "Furthermore, we investigated if PI3K/AKT/mTOR signaling is responsible for DEK-mediated acceleration of tumor cell migration, angiogenesis, and EMT." (PMID 29228721, 2017). "Further functional analysis showed that DEK promotes tumor angiogenesis via VEGF." (PMID 26988756, 2016). "Importantly, we demonstrate that DEK promotes tumor angiogenesis and growth in HIF-1α-dependent and -independent manners." (PMID 26988756, 2016). "Moreover, DEK expression in gastric cancer correlates to tumor size, differentiation, clinical stage, disease-free survival, and overall survival rates." (PMID 27057626, 2016). "Overexpression of DEK promotes epithelial transformation and tumor growth." (PMID 26988756, 2016). "In this study, we demonstrate a novel function for DEK in tumor angiogenesis." (PMID 26988756, 2016). "Thus, we propose a model wherein IRAK1 stimulates tumor signaling and phenotypes both independently and in conjunction with DEK." (PMID 26527316, 2015). "There are several mechanisms by which DEK may mediate inflammation and tumor immunity responses in tumor microenvironments." (PMID 26425120, 2015). "However, DEK-dependent signaling pathways and molecular mediators of DEK-dependent tumor phenotypes in HNSCC are limited." (PMID 26527316, 2015). "Enhanced DEK expression could endow cancer cells with stem cell-like characteristics, fostering tumor advancement and resistance to chemotherapy, underscoring its pivotal role as an oncogenic driver in tumor initiation." (PMID 38920989, 2024). "Furthermore, a recent study showed that DEK influences tumor cell migration and invasion in HCC." (PMID 36768989, 2023). "Furthermore, DEK-silenced Jurkat cells generated a significantly smaller tumor mass in mice." (PMID 35769815, 2022). "However, the molecular mechanisms by which DEK promotes tumor progression are poorly understood." (PMID 32708944, 2020). "Combined, this suggests that targeting DEK expression, or inhibiting its downstream targets, may be an effective therapy that would have both a cytotoxic effect on breast cancer cells and could reactivate the anti-tumor immune response." (PMID 32708944, 2020). "DEK may mediate inflammation and immunity responses in tumor microenvironments." (PMID 31766266, 2019). "DEK can also be recognized by specific antibodies in autoimmune disease or taken up as a functional exogenous protein by nearby cells, in turn stimulating chronic inflammation and inducing more proinflammatory factors that generate progressive tumor microenvironments." (PMID 31766266, 2019). "Thus, plasma DEK level is elevated in parallel to both tumor stage and progression of GC." (PMID 31766266, 2019).